IL6 (interleukin 6)
Diseases named in the same sentence as IL6 in open-access papers (continued):
Sharing a sentence is not in itself a finding about the gene and the disease.
cancer (continued). "Numerous cytokines have been reported to recruit MDSCs in cancer tissues, such as IL-1β, IL-6, IL-4, macrophage colony-stimulating factor, and granulocyte macrophage colony-stimulating factor." (PMID 29326716, 2017). "With this model, we demonstrated that overexpression of IL-6 alone was sufficient to induce prostate epithelium malignant neoplasm." (PMID 28077171, 2017). "SK1 expression is also increased in invasive cancer phenotypes compared with non-invasive cancer cells and results in increased IL-6 levels." (PMID 28241498, 2017). "The TLR-mediated pro-inflammatory cytokine, IL-6, is another integral molecular effector of initiation and growth of malignant tumors." (PMID 29371911, 2017). "The numbers of α-SMA-positive cancer-associated fibroblasts (CAFs) (P = 0.049) and α-SMA-positive CAFs co-expressing p21Waf1/Cif1 (P = 0.038), γ-H2AX (P = 0.065), and IL-6 (P = 0.048) were greater for SH-HCCs than C-HCCs." (PMID 28273155, 2017). "We report an association between inflammatory markers IL-6 and CRP and appetite, and IL-1ra and fatigue in cancer patients with advanced disease." (PMID 28542626, 2017). "Pro-inflammatory cytokines, such as IL-1, IL-6 and TNF-α, are associated with colitis-associated cancer." (PMID 29285251, 2017). "Taken together, evidence linking stress to cancer progression and inflammation provide penetration into the magnitude of modulation of cancer-related cytokines (e.g., IL-6) that appear to alleviate the effects of stress on cancer." (PMID 28676747, 2017). "IL-6 is a critical cytokine in tumorigenesis, and early studies indicated that IL-6 act as a pro-tumorigenic agent in many cancers, implying that it plays an important role in proliferation." (PMID 29162939, 2017). "The study concluded that zerumbone inhibited cancer cell growth through the induction of apoptosis, arrested cells at the G2/M phase, and inhibited the secretion levels of IL-6 in both cancer cells." (PMID 30410707, 2017). "Our group used a novel microfluidics migration platform to assess the migration ability of cancer stem cells in the presence of EC CM and showed the impact of IL-6 pathway in cancer stem cell motility." (PMID 29245982, 2017). "Cancer is associated with inflammation and some of the inflammatory markers such as TNF-α, IL1, IL-6 become increased in HCC and after DEN administration, as both are associated with inflammation." (PMID 28830415, 2017). "To test the effect of endothelial cell-secreted IL-6 on the fraction of cancer stem cells in vivo, we generated IL-6 knockout endothelial cells (sgRNA-IL-6 HDMEC) using CRISPR/Cas9 system." (PMID 29245982, 2017). "Other anti-IL-6 mAbs are in development and have shown promising effect in the treatment of several cancer type." (PMID 28927416, 2017). "There is evidence in the literature that NFkB and AP-1 signaling contributes to cancer cell migration and invasion through the expression of inflammatory cytokines such as IL-6 and TNF-α." (PMID 28427184, 2017). "A computational study was carried out on cancer-related targets including IL-2, IL-6, COX-2 Caspase-3 and Caspase-8." (PMID 28344831, 2017). "In previous studies, both autocrine and paracrine IL-6 signaling increased the invasive and metastatic ability of human cancer cells." (PMID 28725043, 2017). "We found that tocilizumab as well as knock down of IL-6 expression efficiently blocked cancer cell-induced autophagy acceleration, consistent with an important role for IL-6 in autophagy regulation." (PMID 28515477, 2017). "According to the results of our immunofluorescence double staining experiments in cancer cell lines treated with IL-6 or AG490, we found that p-STAT3 activation is more closely linked with vimentin expression than VE-cadherin expression." (PMID 29333928, 2017).
cancer (continued). "Loss of MUC2 and strong expression of IL-6 and CD68 were also detected in serial sections of one specimen from another patient with stage IIA cancer (lower left and lower right)." (PMID 28725043, 2017). "The response then led to Lin28-regulated expression of the anti-inflammatory cytokine interleukin-6 (IL-6) via inhibiting let-7 expression, thus revealing a new mechanism containing cancer cells and immune molecules." (PMID 28147339, 2017). "We preferentially choose Shh and IL-6 because of their overlapping roles in cancer development, progression and possible roles in therapeutic resistance." (PMID 28496132, 2017). "Clinically, as recently demonstrated, IL-6 and IL-8 levels correlate with histologic grade in several cancers and specifically with neovascularization processes." (PMID 29721026, 2017). "Conversely, stimulation with IL6 potentiated the migration of cells with RIP4 knockdown suggesting that sustained STAT3 signaling promotes the metastatic potential of these cancer cells." (PMID 28574510, 2017). "The activation of these receptors promotes an increase in the synthesis and release of pro-inflammatory cytokines (TNF-α and IL-6), collaborating to the development of systemic inflammation existing in cancer cachexia." (PMID 29376055, 2017). "IL-6 is a pro-inflammatory cytokine, which plays an important role also in the progression and immune-regulation in several types of cancers through the activation of the STAT3 pathway." (PMID 29020964, 2017). "In our work, doxycycline not only suppressed the cancer cell-derived chemo-attractants for monocytes, e.g., IL-6 and CCL2, but also directly impaired the migration activity of mouse PBMCs." (PMID 28178994, 2017). "For the first time, this study demonstrates label-free nanotube micro-array platforms using PASE conjugated aptamers for detection of IL-6 protein, an important cancer biomarker." (PMID 28420169, 2017). "Blockade of the IL-6 pathway with a humanized anti-IL-6R antibody (tocilizumab) inhibited endothelial cell-induced motility in vitro and decreased the fraction of cancer stem cells in vivo." (PMID 29245982, 2017). "It has been well established that activation of the signal transduction and activator of transcription 3 (STAT3), a key effector protein of IL-6 signaling, is critical in initiating oncogene transcription and cancer progression." (PMID 28077171, 2017). "CAFs: CSCs manipulate neighboring fibroblasts into cancer-associated cells (CAFs) by the secretion of several factors, including PDGF-α/β b-FGF, IL6 and TGFβ." (PMID 29194401, 2017). "IL-6 is a pleiotropic cytokine, which acts directly on cancer cells to promote their survival and proliferation." (PMID 28650989, 2017). "Siltuximab (CNTO 328), an anti-IL-6 antagonist antibody developed by Janssen Biotech possesses potential benefits in treating various human cancers either as a single agent or in combination with other chemotherapy drugs." (PMID 28927416, 2017). "In the present study, we found that IL-6 secretion is the major mechanism by which RAB3C induces cancer metastasis." (PMID 28784136, 2017). "Interleukin 6 (IL-6) is a multifunctional inflammatory cytokine involved in various biologic processes, including dysimmune diseases and cancers." (PMID 28030810, 2017). "A recent study reported that the prevalence of Corynebacterium correlated with concentrations of IL-6 and C-reaction protein in cancer patients." (PMID 28943876, 2017). "More recently, stress-mediated immune modulation of cytokines including TNF-α, TGF-β, IL-1 and IL-6 have been suggested as indictors of cancer progression, metastasis and recurrence." (PMID 28676747, 2017). "Here, we demonstrated endothelial cell-secreted IL-6 induces cancer stem cell migration and also unveiled the therapeutic potential of IL-6 signaling blockage in HNSCC." (PMID 29245982, 2017).
cancer (continued). "Interleukin-6 is an inflammatory cytokine upregulated in most common human cancers, with increased levels of IL-6 in serum indicating poor prognosis in most cancers." (PMID 28955335, 2017). "We also demonstrated an effect of CDDP/CBP501 on IL-6 production in two other macrophage-cancer cell co-culture systems: (i) human NSCLC cell line NCI-H1299 with human macrophage cell line THP1 and (ii) Ex3ll with mouse peritoneal primary macrophages." (PMID 28969049, 2017). "IL-6 plays a crucial role in tumor microenvironment regulation in a number of cancers, including breast, oral, prostate, and pancreatic cancers." (PMID 28420169, 2017). "In order to evaluate the role of endothelial-cell secreted IL-6 on migration of cancer stem cells, we treated sorted ALDHhighCD44high cells with tocilizumab and allowed the cells to migrate in the presence of EC CM." (PMID 29245982, 2017). "For example, elevated pre-treatment serum IL-6 correlates with a more advanced cancer stage and poorer response to chemotherapy." (PMID 28851415, 2017). "The examination of inflammatory mediators of cancer cachexia will be delimited to interleukin 6 (IL-6), tumor necrosis factor α (TNF-α), and transforming growth factor β (TGF-β) superfamilies' role." (PMID 28785374, 2017). "This explains the phenomenon observed in our previous study, which showed that cancer-derived IL-6-induced T cell suppression in primary MDSCs by activating STAT3-dependent, nuclear factor-κB-mediated long-term IDO overexpression." (PMID 29326716, 2017). "Interleukin-6 is known as a key regulator of immunosuppression in advanced cancer and is responsible for the development of pro-inflammatory and metastatic tumor microenvironments." (PMID 29326716, 2017). "Interleukin 6 (IL-6) is an inflammatory cytokine, which plays a role in cancer metastasis by downregulating E-cadherin." (PMID 29383201, 2017). "The count of TAM, but not Treg (p = 0.42), positively correlated with counts of IL6+ cancer cells (p = 0.001)." (PMID 29048388, 2017). "The expression of RAS oncoproteins in cancer cells promotes the secretion of IL6, IL8 and CXCL1, which recruit macrophages." (PMID 29194401, 2017). "Among the candidate genes on this list, we focused on the IL-6 cytokine as it is reported to have multiple functions including the maintenance of cancer stem cells and inhibition of apoptosis." (PMID 28924147, 2017). "A number of studies have also highlighted the role of IL-6 in the acquisition of chemo and radioresistance and stem cell phenotype in cancer cells." (PMID 28978005, 2017). "In total, 10 proteins had an estimated AUC of at least 0.7 and were significantly associated with cancer status, including hK11, PRSS8, IL-6, MK, and CXCL13." (PMID 29051715, 2017). "Specifically, it demonstrates the relation between IL-6, a major component of inflammaging, and cancer development and progression." (PMID 28966805, 2017). "A link between S1P and STAT3 signaling is exemplified by studies showing that S1P enhances colitis associated cancer via a malicious amplification loop involving SK1, S1P1, NF-κB, STAT3 and IL-6." (PMID 28241498, 2017). "Cancer cells resistant to chemotherapy and oncoprotein-targeted drugs display increased IL-1α, IL-6, IL-8, TNF-α, HGF, EGF, VEGF, GM-CSF and SDF-1α expression." (PMID 28928376, 2017). "In contrast, the full endothelial cell-secreted milieu is very efficient at inducing cancer stem cells migration, and within this milieu IL-6 plays a critical role as demonstrated in several blocking experiments." (PMID 29245982, 2017). "TIMP1, another downstream molecule of IL6, has been reported to regulate the cancer cell survival, modulate the proteolytic activity in ECM, and negatively regulate the adipocyte differentiation." (PMID 28333977, 2017). "Numerous reports showed that SOCS3 defects are responsible for sustained IL-6/STAT3 signaling in human cancers." (PMID 29326716, 2017).
cancer (continued). "Due to this ability to promote invasiveness of cancer cells and the spreading of senescence to neighboring cells IL-6 and IL-8 are of special interest." (PMID 29206223, 2017). "Alantolactone has been reported to have anti-inflammatory and anti-cancer effects through IL-6-induced signal transducer and activator of transcription 3 (STAT3) signaling pathway." (PMID 28706484, 2017). "One important mechanism is interfering with the activation of IL-6/Jak-2/STAT3 signalling pathway which was found to have a pivotal role in cancer development and progression." (PMID 28970500, 2017). "Evidence also showed for a novel double-paracrine mechanism whereby cancer epithelium produces KLK4 to activate PAR-1 in the surrounding stroma, which in-turn releases cytokines (IL-6) that stimulate cancer cells to proliferate and increase production of KLKs." (PMID 29291033, 2017). "These polarizations are adjusted by cytokines, such as macrophage-colony-stimulating factor (M-CSF), transforming growth factor (TGF)-β, interleukin (IL)-6 and IL-10 in the cancer microenvironment." (PMID 28583114, 2017). "A correlation between the IL-6 secretion of CD68 macrophages and a higher level of IL-6 in cancer cells was observed." (PMID 28725043, 2017). "An inverse correlation of BChE and the inflammatory markers CRP and IL-6 has been reported in a non-cancer cohort." (PMID 29113384, 2017). "IL-6 is a multifunctional player in cancer progression—it is known for its role in pro-inflammatory immune responses, cell survival, apoptosis and proliferation." (PMID 28402963, 2017). "The Treg and TAM counts surrounding the cancer lesion and IL6-positive cancer cell counts were evaluated against clinicopathological variables." (PMID 29048388, 2017). "Two such adipokines are VEGF and IL-6, which were increased in our experiments; both of which were reported to induce cancer cell survival via enhanced resistance to chemotherapy in PDAC." (PMID 28632775, 2017). "We found that cancer-derived interleukin-6 (IL-6) induces the immunosuppressive ability of MDSCs by activating the STAT3/IDO signaling pathway, but the detailed molecular events are unclear." (PMID 29326716, 2017). "Inflammatory cytokines such as IL-6, CRP, and TNF-alpha have been shown to be associated with cancer incidence." (PMID 29045425, 2017). "TNFR2 expression has been shown to be induced by either TNF or TNF in combination with IL-6 in cancer cell lines." (PMID 29163543, 2017). "Some small molecule compounds inhibiting IL-6 and its downstream targets have also been developed and evaluated in preclinical and clinical studies of various human cancers." (PMID 28927416, 2017). "IL-6, TNF-α, and TGF-β are cytokines that have been mechanistically linked to skeletal muscle wasting and disrupted metabolic homeostasis during cancer cachexia." (PMID 28785374, 2017). "Persistent activation of the IL-6-signaling pathway has been observed in many types of tumors, and contributes to carcinogenesis and cancer progression." (PMID 28208810, 2017). "IPA also identified potential upstream regulators, which play a key role in cancer invasiveness: interleukin-6 (IL-6), IL1B and transforming growth factor, beta-induced (TGFBI) were the top three upstream activated regulators (P< .05)." (PMID 28632775, 2017). "IL-6 is a cytokine that plays a major role in several inflammatory diseases, such as rheumatoid arthritis, Crohn’s disease, and several other cancers, such as myeloma." (PMID 28325295, 2017). "It is possible that our cancer patients have higher levels of IL-6 in the circulation, as been shown in other cancer patients." (PMID 28827632, 2017). "Based on these understandings, recent studies have been focused on targeting IL-6 or IL-6 signaling pathways in cancer patients." (PMID 28077171, 2017).
cancer (continued). "These previous reports demonstrated the effects of extrinsic IL-6 on cancer cells, and showed that non-cancer cells (such as cancer-associated fibroblasts) in various cancers, as well as MSC41, indeed secreted IL-6." (PMID 28951614, 2017). "Modulation of SOCS-3 expression, which is involved in regulation of activities of IL-6, is sufficient to counteract the effect of enzalutamide on stemness genes in cancer cells." (PMID 29214142, 2017). "In mouse models of colitis-associated cancer that combined the treatment of AOM and DSS, IL-6 was mainly expressed by infiltrating macrophages, dendritic cells, and T cells during tumorigenesis." (PMID 28852270, 2017). "In another study, LIN28B was found to link molecularly inflammation and cancer via a positive feedback loop involving NF-κB activation and derepression of the let-7 regulated gene IL-6." (PMID 28400788, 2017). "IL-6 is a multifunctional cytokine produced by macrophages, endothelial cells, T lymphocytes but also cancer cells like breast and prostate." (PMID 28389628, 2017). "IL-6 is also elevated in lots of cancers and is a potential regulator of stem cell renewal and proliferation." (PMID 28507278, 2017). "After cancer cells were exposed to IL-6 for 24 h, a spindle-shaped morphology was observed, and a near complete loss of epithelial features occurred, including E-cadherin, and increased expression of vimentin, α-SMA and N-cadherin was detected." (PMID 28846080, 2017). "We demonstrated that inhibition of endothelial cell-activated IL-6 pathway prevented EMT in cancer stem cells and inhibited their migration, unveiling the role of IL-6 on cancer stem cell motility." (PMID 29245982, 2017). "Biomarkers IL-6 and IL-8, VEGF, MMP-9, MCP-1, IL-11, IGF-1, and Rantes are associated with different stages of cancer." (PMID 28763032, 2017). "It has been shown that IL-6 serves as an anti-apoptotic factor and also a survival factor in certain cancers, such as hepatocellular carcinoma." (PMID 28325295, 2017). "Our study is the first to reveal the relationship between exocytic RABs and cytokine secretion, and it further solidifies the role of RAB-regulated IL-6 autocrine signaling in cancer progression." (PMID 28784136, 2017). "The IL-6 driven STAT3 phosphorylation and activation in OxS has been shown before and has been linked with inflammation, cell injury, and cancer, but the potential role of SP-A2 in this process is novel." (PMID 29202868, 2017). "Elevated circulating IL-6 can be observed in cachectic cancer patients and preclinical models alike and is strongly correlated to body weight and muscle mass loss." (PMID 28785374, 2017). "NFκB-triggered positive feedback for IL-6 signaling, also known as inflammation amplifier, induces various molecules to create a microenvironment which promotes cancer development." (PMID 28903416, 2017). "In fact, there are many other target genes of NFκB, such as IL-6 and iNOS, all of these genes are also important in the cancer stem cell self-renewal, chemoresistance and/or metastasis of tumors." (PMID 28591725, 2017). "IL-6 can be produced in an autocrine fashion in both breast, and ovarian, cancer and therefore is an important step in tumorigenesis." (PMID 29262529, 2017). "N-3 PUFAs are beneficial as a dietary supplement for cancer patients as they reduce the level of inflammatory cytokines, including IL-2, IL-6, as well as TNF-α, and promote anti-inflammatory activities." (PMID 28410575, 2017). "This corresponded with an accuracy of 77.1% as well as significantly lower patient survival rates and positive immunohistochemical staining of IL-6 in cancer cells." (PMID 28487810, 2017). "Together with the cancer cell they are a source for immunosuppressive factors like IL-6, IL-11, COX2 and also for VEGF, all of which are STAT3 induced as well as being inducers of immunosuppressive STAT3 signaling." (PMID 28402937, 2017).